INS (insulin)
Diseases named in the same sentence as INS in open-access papers (continued):
Sharing a sentence is not in itself a finding about the gene and the disease.
Hyperglycemia (continued). "Hyperglycemia levels most likely due to poor insulin synthesis could be corrected by using mediational therapies involved in increasing insulin levels." (PMID 32503113, 2020). "Ninth, intraperitoneal administration of AGE-BSA has been reported to impair glucose tolerance in mice in association with decrease in acute insulin secretion, AGE may augment foam cell formation of macrophages by further deteriorating hyperglycemia." (PMID 32646003, 2020). "Premixed insulin analogue regimens are recommended to China patients as initial insulin therapy partially may be due to the factor that isolated postprandial hyperglycemia is more prominent in Chinese patients when compared to white patients." (PMID 32090123, 2020). "Hyperglycemia may induce increased peripheral utilization of insulin and reduce insulin transport into the brain, ultimately producing brain insulin deficiency." (PMID 33202379, 2020). "Hence, peripheral resistance to insulin implies unrestrained hepatic glucose production, and suppression of muscle and adipose glucose uptake, resulting in hyperglycemia." (PMID 32128655, 2020). "Intriguingly, in Peroxiredoxin 6 knockout (Prdx6-/-) mice model, we previously reported as the absence of Prdx6, induces a phenotype similar to early-stage of T2DM caused by both reduced glucose-stimulated insulin secretion and increased skeletal muscle insulin resistance with mild hyperglycemia." (PMID 32316601, 2020). "Similarly, in diabetic patients with severe hyperglycemia and acute coronary syndromes, rapid correction of hyperglycemia via intravenous insulin (12 h) increases platelet responsiveness to NO•." (PMID 32508651, 2020). "Moreover, intraperitoneal injection of STZ exerted a necrotic effect on insulin-producing pancreatic β-cells leading to hyperglycemia and a significant decrease in insulin secretion within 48 after its injection." (PMID 31998774, 2020). "Higher-quality complex carbohydrates with lower glycemic indexes are preferred since they may help reduce the need for insulin as well as decrease postprandial hyperglycemia." (PMID 33371325, 2020). "It is defined by the presence of severe hyperglycaemia associated with insufficient or no circulating insulin, occurring mainly before 6 months of age and rarely between 6 months and 1 year." (PMID 33102403, 2020). "Hyperglycaemia occurs frequently in ST‐elevation myocardial infarction (STEMI) and is associated with poor outcomes, for which continuous insulin infusion therapy (CIIT) may be beneficial." (PMID 31922020, 2020). "Accordingly, administration of insulin might ameliorate the DM hyperglycemia and improve oxidative stress." (PMID 32695298, 2020). "Moreover, insulin is the most effective hormone for the treatment of hyperglycemia by mediating direct and indirect actions to lower hyperglycemia." (PMID 33905470, 2020). "Knowing the serum insulin levels in ill babies with hyperglycaemia may justify insulin use or otherwise early in the management of NNH." (PMID 32637004, 2020). "The QTL derived from SJL, 129P2, and C3H were characterized not only by hyperglycemia but also by a lack of insulin, indicating that β-cell failure is underlying the diabetogenic effect of the QTL." (PMID 33133152, 2020). "Many studies have attributed increased level of stress hormones which are known to stimulate gluconeogenesis as being important in the pathogenesis of hyperglycaemia in ill neonates but the importance of serum insulin in this respect needs to be further studied." (PMID 32637004, 2020). "Furthermore, allicin improved blood pressure, insulin bioavailability and decreased hyperglycemia by the modulation of GLUT4 and IRS proteins in muscle." (PMID 33203103, 2020). "The effect of cytokines on insulin production in hyperglycemia was found." (PMID 32587797, 2020). "This suggests that early hyperglycemia may be intrinsic to low gestational age when insulin insensitivity is part of development." (PMID 33004691, 2020).
Hyperglycemia (continued). "The transient hyperglycaemia observed in DIO mice after the first single DMPP injection was associated with a fourfold increase in plasma adrenaline 80 min after injection (p ≤ 0.01), while circulating noradrenaline and insulin were unaltered." (PMID 32140744, 2020). "A long-acting glucagon-like peptide 1 receptor agonist dulaglutide could provide glycemic control while reducing the insulin dose and injection frequency in the inpatient care for GC-induced hyperglycemia." (PMID 32381085, 2020). "Treatment of hyperglycemia with insulin administration has positive effects on in patients." (PMID 32815547, 2020). "However, oral administration anserine in the amount of 156 mg/day can enhance whole-body insulin sensitivity in subjects with hyperglycemia." (PMID 32072297, 2020). "We treated Kuma mice with insulin implants for 4 weeks and found that this could rescue the mice from hyperglycemia." (PMID 32699230, 2020). "Furthermore, metabolic syndrome and the resulting insulin and leptin resistance and hyperglycaemia have pro-inflammatory effects with profound consequences on the BBB." (PMID 33322180, 2020). "Intraoperative stress hyperglycemia is a common clinical issue due to a transient decrease in insulin responsiveness; it may persist for days or weeks after major surgery." (PMID 33301501, 2020). "On the other hand, overexpression of TMBIM6 by adenoviral gene transfer dramatically improved glucose metabolism in lean and diet-induced obese mice and reversed hyperglycemia in db/db mice, which was accounted for by lower gluconeogenesis and improved insulin sensitivity." (PMID 32394396, 2020). "Additionally, between three to seven days post-injury, severely injured trauma patients developed increased lipid metabolism, insulin resistance, and hyperglycemia (“Hypermetabolic state II”)." (PMID 31974669, 2020). "Time to resolution of hyperglycemia, ketosis, acidemia, and ketoacidosis, and the length of hospitalization in dogs with diabetic ketoacidosis treated with IM insulin lispro (Group L) and treated with IV continuous rate infusion (CRI) of regular insulin (Group R)." (PMID 33195532, 2020). "Hesperidin decreased the levels of STZ-induced hyperglycemia and pro-inflammatory cytokines and increased the nociceptive threshold, motor nerve conduction velocity, sensory nerve conduction velocity, insulin levels, and Na-K-adenosine triphosphate (ATP)ase activity in the diabetic rats." (PMID 32977511, 2020). "Guidelines on detection and management of hyperglycaemia in hospitalized patients (in the non-critical care setting) recommend initiation of sliding scale insulin (aspart) therapy or other insulin regimens in case of hyperglycaemia during glucocorticoid treatment." (PMID 32539810, 2020). "The results, obtained in this work, also confirmed by other researchers, with regard to decreased IGFBP-1 in babies born to mothers with GDM, can be explained by hyperglycemia and an increased insulin concentration in the fetus, which inhibits the production of IGFBP-1 in the liver." (PMID 33053704, 2020). "A recent study from Italy comparing hyperglycemia control in critically ill COVID-19 patients with pre-existing DM associated hyperglycemia without insulin infusion with higher risk of severe disease." (PMID 33198177, 2020). "In turn, the state of hyperglycemia impairs peripheral IR and insulin action." (PMID 33905470, 2020). "Similarly, another study in a T2D model utilised the ER chaperone tauroursodeoxycholic acid (TUDCA), which led to normalisation of hyperglycaemia, enhanced insulin action and restoration of insulin sensitivity." (PMID 31396860, 2020). "Moreover, hyperglycemia contributes to vascular NO• resistance, such that glucose lowering, with long-term insulin treatment (3.5 years), improves brachial artery vasodilatation to SNP in patients with T2DM (Vehkavaara and Yki-Järvinen, 2004)." (PMID 32508651, 2020).
Hyperglycemia (continued). "Irp2−/− mice showed fasting hyperglycemia (WT, 6.06 ± 0.23 versus Irp2−/−, 7.17 ± 0.39 mmol glucose/L; p = 0.02) and reduced basal plasma insulin concentrations (WT, 1.87 ± 0.773 versus 0.489 ± 0.105 ng/ml insulin, p < 0.05)." (PMID 31941883, 2020). "In addition, oral administration of taurine can ameliorate structural abnormalities of the pancreas, while improving insulin production by pancreatic β-cells and whole-body insulin sensitivity in subjects with hyperglycemia." (PMID 32072297, 2020). "Hence, insulin presents a double-edged agent, being required for controlling hyperglycemia while concomitantly promoting resistance to insulin in the glycemic context." (PMID 32128655, 2020). "Furthermore, hyperglycemia impairs skeletal muscle cell insulin sensitivity, pancreatic β-cell insulin secretory capacity, and endothelial cell function within in vitro experimental models." (PMID 33178135, 2020). "It is one of the most prevalent chronic diseases and leads towards severe complications such as increase in production of reactive oxygen species (ROS), impairment of antioxidant enzymes, hyperglycemia, dislipidemia, alteration in insulin signaling pathway, and ROS-induced cellular damage." (PMID 32256963, 2020). "Thus, our observations indicate SPs reduced hyperglycemia by potentiating glucose-stimulated insulin secretion and decreasing insulin resistance, whereas metformin decreased serum glucose levels mainly by enhancing insulin sensitivity." (PMID 31991596, 2020). "If insulin secretion is insufficient, hyperglycemia and consequent GDM will develop." (PMID 32646482, 2020). "SCFAs might have increased glycolysis/gluconeogenesis pathways and inhibited insulin signaling at the peripheral tissues, resulting in hyperglycemia in women with GDM." (PMID 32500037, 2020). "AD-KD decreased the response to insulin and it may induce hyperglycemia when glucose availability increases." (PMID 33041517, 2020). "Insulin-induced hypoglycemia enhances vagal activity, while hyperglycemia depresses vagal tone." (PMID 32326226, 2020). "The authors of a small retrospective study suggested that insulin treatment by itself might be a stronger predictor of ROP than hyperglycemia." (PMID 33306685, 2020). "In addition, it reduced hyperinsulinemia and hyperglycemia, improved glucose tolerance, ameliorated plasma leptin levels, decreased visceral fat content, increased plasma adiponectin levels, and improved insulin sensitivity." (PMID 32977511, 2020). "In the absence of noxious stimuli or with moderate disruptions to the islet microenvironment such as low-level inflammation or hyperglycemia, small EVs transfer regulatory molecules among cells within islets in order to coordinate insulin production and secretion and preserve β-cell viability." (PMID 32595604, 2020). "Whey protein may be involved in decreasing postprandial hyperglycemia and could improve the insulin response by different mechanisms." (PMID 32958070, 2020). "To investigate whether hyperglycemia and insulin depletion are sufficient to generate oxidative stress in nigrostriatal neurons, we used STZ‐treated diabetic mice." (PMID 32666590, 2020). "Thus, a conservative adjustment would be to add 60 mg/dL (3.3 mmol/L) to the current sensor glucose value when calculating the insulin dose to correct hyperglycemia." (PMID 32256447, 2020). "This seems counter-intuitive knowing that, in vivo conditions, hyperglycemia will induce increases in the plasma insulin level, thus insulin could act as a protective agent against IRI through the activation of the Akt/hexokinase II (HKII) pathway." (PMID 32326182, 2020). "Similarly, PPARα KO mice develop marked age-dependent hyperglycemia, and after 24-h fasting, severe hypoglycemia accompanied by elevated plasma insulin concentrations." (PMID 32708786, 2020).
Hyperglycemia (continued). "Our experimental diabetic model showed low levels of insulin that could explain hyperglycemia, a decrease in GLUT4 protein expression and an increase in IRSs protein expression." (PMID 33203103, 2020). "The deficiency or absence of insulin causes hyperglycemia; hence, an increase in the level of free radicals is noticed due to the oxidation of the increased glucose." (PMID 32509990, 2020). "The activation of pro-inflammatory pathways can negatively impact insulin sensitivity and may drive the hyperglycemia observed with the IV dextrose intervention." (PMID 32977395, 2020). "The four patients required oral hypoglycemic agents or insulin therapy to control hyperglycemia." (PMID 32708349, 2020). "Reduced insulin sensitivity in the liver, muscle, and adipose tissue, and progressive dysfunction of pancreatic β-cells lead to impaired insulin secretion, and finally result in hyperglycemia." (PMID 33287318, 2020). "Together, these findings suggest insulin or peripheral hyperglycemia may have effects on SST neurons and pituitary somatotrophs to control GH release in addition to the effects of low glucose on GHRH neurons." (PMID 33148883, 2020). "Restoration of adipsin ameliorated hyperglycemia by augmenting insulin secretion in vivo." (PMID 32079203, 2020). "Reductions in insulin sensitivity and insulin secretion are the hallmarks of T2DM, and a large number of studies have revealed that hyperglycemia and hyperlipidemia are critical risk factors for islet β-cell dysfunction, which are known as β-cell glucotoxicity and lipotoxicity." (PMID 33117454, 2020). "However, since the human insulin monomers readily aggregate into multimers, the recombinant wild type human insulin displays a delay in treating hyperglycemia." (PMID 31918694, 2020). "Since hyperglycemia would influence the glucose level in bone marrow, insulin therapy for 5 days may improve growth circumstances of mature neutrophils in bone marrow and then may contribute to the improvement of neutrophil phagocytosis." (PMID 32993618, 2020). "Moreover, intravenous infusion of PGE2 to rats decreased insulin secretion in response to glucose and, by using a transgenic mouse model overexpressing COX2 and PGE2 synthase-1, reduced insulin level and hyperglycaemia were demonstrated." (PMID 32350565, 2020). "Hyperglycemia leads to increased DNA methylation at Pdx1 and INS in β cell." (PMID 32815547, 2020). "Insufficient amounts of insulin paired with excess glucagon is a recipe for hyperglycemia." (PMID 32582035, 2020). "Furthermore, insulin treatment of Akita diabetic mice normalized hyperglycemia and attenuated urinary ACE2 shedding, albuminuria, and renal ADAM17 expression." (PMID 32026607, 2020). "Hyperglycemia-induced reactive oxygen species (ROS) have been shown to reduce insulin secretion from pancreatic β-cells, to impair insulin sensitivity and signaling in insulin-responsive tissues, and to alter endothelial cells function in both type 1 and type 2 DM." (PMID 32660119, 2020). "Furthermore, metabolic changes have also been observed, such as hyperglycaemia secondary to a reduction in insulin release, as well as insulin resistance." (PMID 32476043, 2020). "However, under circumstance of hyperglycemia, the response of β-cell function to insulin is reduced, and it is thus inaccurate to assess the β-cell function by glucose challenge." (PMID 32775460, 2020). "STZ administration decreased the production of insulin and increased blood glucose (hyperglycemia)." (PMID 32104545, 2020). "Insulin is currently used to control post-operative stress hyperglycemia." (PMID 33097799, 2020). "Moreover, maternal hyperglycemia makes the fetus to secrete more insulin to handle excessive sugar that passes from the mother to the fetus via placenta." (PMID 33170888, 2020).
Hyperglycemia (continued). "This delay may be caused by the fish being stimulated to secrete glucagon and somatostatin hormones under the stress of hyperglycemia, thereby inhibiting the secretion of insulin and delaying the change in insulin in response to plasma glucose." (PMID 33178047, 2020). "Myricitrin and vitamin E were improved hyperglycemia and increased insulin level." (PMID 32821355, 2020). "Likewise, skeletal muscle and hepatic insulin sensitivity, insulin secretory capacity, and vascular function are impaired by exposure to experimental hyperglycemia in vivo, even in healthy individuals with normal glucose tolerance." (PMID 33178135, 2020). "PRS adjusted for PS with or without exogenous insulin infusion was significantly associated with hyperglycemia occurrence during the neohepatic phase." (PMID 33301501, 2020). "The observed diminution in VMH GE electrophysiological response to local physiological (postmeal) hyperglycaemia by HFD feeding would be expected to reduce the VMH GE neuronal activated induction of peripheral insulin action and glucose disposal following a meal." (PMID 32704560, 2020). "In mammals, insulin is secreted by the pancreatic β cells in response to high blood sugar levels and promotes the cellular uptake and utilization or storage of glucose to prevent hyperglycemia." (PMID 32448994, 2020). "Hence, in prolonged critically ill patients, tight glucose control was realized with similar serum insulin concentrations as in patients in whom moderate hyperglycemia was tolerated, in the presence of severe hepatic insulin resistance." (PMID 32448392, 2020). "Hyperglycemia elevates O-GlcNAc levels in pancreatic beta cells, which seems to modulate insulin production and release, but the exact site(s) of interference has not been clarified yet; among others, modifying transcriptional factors and epigenetic regulations have been proposed." (PMID 31466420, 2019). "Exposure of β-cells to hyperglycemia might promote efflux of insulin secretory granules from the β-cell, leaving less insulin available for release in response to further hyperglycemia." (PMID 31066759, 2019). "In conclusion, we should pay more attention to FBG, and timely intervention for hyperglycemia, by using insulin or other glucose-lowering medication, may bring more benefit for patients with myocardial infarction." (PMID 31737681, 2019). "However, the liver-specific CB1 knockout mice showed less steatosis, hyperglycemia, dyslipidemia, and insulin and leptin resistance compared to wild-type mice fed with a HFD." (PMID 31121839, 2019). "Even though the exact source of methylated cfDNA remains unknown, the increase in total insulin cfDNA, found in our study, may reflect this increased proinflammatory cytokine profile and/or other systemic effects of hyperglycemia during pregnancy." (PMID 31428654, 2019). "A pooled analysis reported that isoflavones can improve hyperglycemia, glucose tolerance, and circulating insulin concentration, and can also stimulate phosphorylated AMP-activated protein kinase and acetyl-CoA carboxylase to increase glucose uptake and fatty acid oxidation." (PMID 31731672, 2019). "Thus, the association between potassium categories and variability can be discussed in context of glucose control by insulin therapy, which is beneficial for critically ill patients with stress-induced hyperglycaemia." (PMID 31486927, 2019). "However, a chronic exposure to fructose can indirectly induce hyperinsulinemia as a consecutive effect of hyperglycemia and of insulin’s reduced efficacy in peripheral tissues." (PMID 31835800, 2019). "Transgenic mice that over-expressed rat IGFPB1 downstream of the mouse phosphoglycerate kinase promoter have fasting hyperglycemia, hyperinsulinemia and glucose intolerance, possibly due to enhanced gluconeogenesis, hepatic insulin resistance, and increased serum gluconeogenic substrate." (PMID 30392760, 2019).